EGFR (epidermal growth factor receptor)
Diseases named in the same sentence as EGFR in open-access papers (continued):
Sharing a sentence is not in itself a finding about the gene and the disease.
glioblastoma (continued). "EGFR gene mutations activating mTOR have been studied in colorectal cancers, glioblastomas (GBM), and non-small-cell lung cancer (among others)." (PMID 34205611, 2021). "N-cadherin is also overexpressed in advanced stages of prostate, colorectal, and ovarian cancer and in the latter after stimulation of the EGFR pathway, a protein that is overexpressed in glioblastoma and could be one of the causes of the EMT phenotype in this tumor." (PMID 34073238, 2021). "Epidermal Growth Factor Receptor variant III (EGFRvIII) is an active mutant form of EGFR that drives tumor growth in a subset of glioblastoma (GBM)." (PMID 32547705, 2020). "Furthermore, functional studies showed that overexpression/downregulation of EGFR could partially rescue the inhibition/promotion caused by silencing/elevating LPP-AS2 in glioblastoma cells." (PMID 32962742, 2020). "Glioblastoma (GBM) is a universally lethal tumor with frequently overexpressed or mutated epidermal growth factor receptor (EGFR)." (PMID 33087132, 2020). "Since amplification and/or mutations in EGFR represent a genetic abnormality in primary glioblastoma multiforme (GBM), EGFR has been regarded as a pivotal target for GBM studies." (PMID 31617054, 2019). "A significant research analysis in glioblastoma of approximately 198 patients has shown the prevalence of amplification-linked extrachromosomal mutations due to which there are momentous mutations in oncogenes such as PDGFRA or EGFR in glioblastoma due to environmental effects." (PMID 31285839, 2019). "Additionally, EGFR fusion and deletion variants are largely distributed in glioblastoma patients." (PMID 31013819, 2019). "In addition, glioblastoma with amplification of EGFR might describe additional mutations in the EGFR gene." (PMID 31013819, 2019). "In addition, multiple EGFR mutations found in glioblastoma, including EGFRvIII, produce a conformational change in the extracellular domain that may promote pro-growth signaling and also renders the mAb806 epitope accessible." (PMID 31903167, 2019). "However, some studies solved the delivery issue of this agent using direct intracranial infusion; the cetuximab successfully blocked glioblastoma cell invasion in a xenograft model, although this was found only in cells with high expression of EGFR and its variant EGFRvIII." (PMID 31013819, 2019). "EGFRvIII, a rearranged variant of EGFR frequently expressed and associated with poor prognosis in Glioblastoma Multiforme (GBM), and also found in breast and lung carcinoma, was recently found to be expressed in glioma stem cell lines." (PMID 30249178, 2018). "Nearly 40–50% of glioblastoma tumors show alterations (amplification, truncation, or mutations) of epithelial growth factor receptor (EGFR) resulting in an uncontrolled multiplication and expression of gene encoding normal EGFR or truncated form called EGFRvIII." (PMID 30374421, 2018). "Human primary glioblastomas (GBM) often harbor mutations within the epidermal growth factor receptor (EGFR)." (PMID 29293494, 2018). "Epidermal growth factor receptor (EGFR) mutations and amplifications are frequently reported in glioblastoma multiforme (GBM) patients." (PMID 28611289, 2017). "The mutant Type III variant of epidermal growth factor receptor (EGFRvIII) is present in approximately one-third of glioblastoma (GBM) patients." (PMID 28412740, 2017). "However, a recent study has demonstrated that improved survival of glioblastoma patients benefiting from metronomic temozolomide-based therapies and showing an EGFR overexpression is associated with activated EGFR/PI3K/Akt pathway independently of the presence of EGFRvIII." (PMID 28785587, 2017).
glioblastoma (continued). "Here, we found that several of the most frequently mutated genes in glioblastoma including: EGFR, PTEN, NF1, PIK3R1, RB1, PDGFRA and QKI possessed high 5 hmC levels across intronic regions and further loss of 5 hmC in tumours may reflect a loss of genome integrity." (PMID 27886174, 2016). "Ligand-mediated chronic activation of EGFR is necessary for gliomagenesis in mice, and this association might be consistent with our finding of time-stable, elevated serum EGFR and ErbB2 levels in glioblastomas." (PMID 26906551, 2016). "For example, glioblastoma samples with mutations in EGFR’s dimerization interface have higher levels of both EGFR and phosphorylated EGFR (Y992 and Y1173) proteins than patients with other EGFR mutations, suggesting that EGFR signaling is stronger in these patients." (PMID 26485003, 2015). "The aggressive and rapidly lethal brain tumor glioblastoma (GBM) is associated with profound tissue stiffening and genomic lesions in key members of the epidermal growth factor receptor (EGFR) pathway." (PMID 25000176, 2014). "However, the most common EGFR variant in glioblastoma, EGFR type VIII, which harbors a deletion of 267 amino acids in the extracellular domain – leading to a receptor that is unable to bind ligand but is constitutively active – is downregulated after Cbl-mediated ubiquitination." (PMID 24295852, 2014). "Previous studies have shown that regulation of the EGFR pathway plays an important role in glioma progression, and certain EGFR genotypes may be related to glioblastoma risk, indicating that germline EGFR polymorphisms may have important implications in carcinogenesis of glioma." (PMID 22662167, 2012). "The epidermal growth factor receptor (EGFR), a type I tyrosine kinase receptor, has been associated with numerous malignancies including breast, lung, head and neck, bladder, colorectal, ovarian, and prostate carcinomas, as well as with the most common form of brain tumor, glioblastoma." (PMID 17437646, 2007). "For instance, intravenous delivery of EGFR-targeted oHSV1 (gD:SD2) significantly inhibited tumor growth in a mouse model of glioblastoma multiforme." (PMID 41403403, 2026). "An expanded access program of depatuxizumab mafodotin for patients with progressive glioblastoma explores the relationship between tumor EGFR expression and outcomes." (PMID 41632538, 2026). "Our results recommend OV-encoded dual-targeting antibodies and more specifically the Db-TriTE-encoding oAd Ad5/3-DMFE for dual-targeting of EGFR and c-MET frequently co-expressed in NSCLC, glioblastoma, and colorectal cancer." (PMID 41552759, 2026). "Glioblastomas, predominantly IDH-wild-type, exhibit aggressive molecular features including TERT promoter mutations, EGFR amplification, PTEN loss, and chromosome 7/10 alterations, leading to rapid growth and poor outcomes." (PMID 41596318, 2026). "U2-AuNP significantly suppressed the proliferation and invasion of U87 human glioblastoma cell lines, prolonging the survival of glioblastoma-bearing mice by obstructing the EGFR-related pathway." (PMID 40771723, 2025). "EGFR (Epidermal Growth Factor Receptor) mutations cause oncogenic signaling in non-small cell lung cancer (NSCLC) and glioblastoma, hence increasing tumor growth and resistance against EGFR tyrosine kinase inhibitors (TKIs)." (PMID 40430848, 2025). "The study demonstrated preliminary safety and bioactivity of CART EGFR IL13Rα2 cells in recurrent glioblastoma, but evidence of efficacy remains inconclusive and requires confirmation in larger cohorts with longer follow-up periods." (PMID 41301694, 2025).
glioblastoma (continued). "The most common form of the mutant EGFR in glioblastoma is EGFRvIII, which harbors an in-frame deletion of exon 2–7, resulting in truncation of the extracellular domain." (PMID 40362634, 2025). "For instance, a study utilising EGFRvIII-CAR-T cells engineered to secrete EGFR-specific BiTEs demonstrated enhanced elimination of heterogeneous glioblastoma cells in murine models." (PMID 40624498, 2025). "Early-phase clinical studies of Depatux-M in recurrent EGFR-amplified glioblastoma reported notable disease control rates, especially when combined with temozolomide." (PMID 40918539, 2025). "In glioblastoma, exons 2–7 of EGFR are often deleted, resulting in the constitutively active mutant EGFRvIII." (PMID 41030947, 2025). "EGFR amplification in recurrent tumors differs from that in primary glioblastomas, with a concordance correlation coefficient of 0.65." (PMID 40197845, 2025). "EGFR amplification is found in about 60% of patients with glioblastoma, resulting in tumorigenesis and tumor proliferation." (PMID 39796751, 2025). "Compared to nuclear FABP7-negative, immunoreactivity of nuclear FABP7 in EGFR-expressing glioblastoma specimens correlates with poor survival." (PMID 40097417, 2025). "For example, researchers have shown that the copy number of ecDNA containing EGFR was identified as the primary driver of elevated EGFR transcription levels in EGFR‐containing glioblastoma (GBM)‐derived glioma stem cells." (PMID 40984821, 2025). "Osimertinib and afatinib were chosen as the EGFR inhibitors based on previous literature demonstrating efficacy in glioblastoma." (PMID 41497449, 2025). "It is frequently observed that deletions of EGFR in glioblastoma, not only in the ECD, but also in the C‐terminal tail region, are collectively termed EGFRvIV." (PMID 40859900, 2025). "We assumed that both aptamers [18F]FB-GR20 and [18F]FB-Gol1, labeled with the radioactive label 4-[18F]-benzylazide, should selectively accumulate on PET scan in glioblastoma tissue with EGFR overexpression." (PMID 41473440, 2025). "This pro-invasive role involves GBP1’s association with EGFR or EGFRvIII, inducing MMP1 expression in glioblastoma." (PMID 40564939, 2025). "In glioblastoma cells, the EGFR interacts with the system xc(−) transporter, promoting its cell surface expression, glutamate export and cysteine uptake." (PMID 39433211, 2025). "This work demonstrates that radiopharmaceuticals [18F]FB-Gol1 and [18F]FB-GR20 bind to rat 101.8 glioblastoma and can serve as promising drug candidates for the selective diagnosis of EGFR expression in glial tumors." (PMID 41473440, 2025). "To further assess the diagnostic potential of APLP1+ EVs for brain diseases, we evaluated their expression in the blood of patients with glioblastoma multiforme (GBM) exhibiting EGFR and EGFRviii expression." (PMID 39742488, 2025). "EGFR signaling plays a central role in glioblastoma development, contributing to tumor initiation, sustained growth, infiltration, and resistance to therapy." (PMID 40940872, 2025). "Our combination treatment is particularly relevant considering the complex molecular biology of glioblastoma in patients, including EGFR alterations and epigenetic dysregulation." (PMID 41497449, 2025). "The CD133 and EGFR-specific antibody fragments on the T-cell membrane can enable the embedded nanomaterials to precisely recognize glioblastoma (GBM) tissues." (PMID 40284476, 2025). "This inhibition is crucial because EGFR signaling is often overactive in glioblastoma, promoting cell survival and proliferation." (PMID 41009025, 2025). "A series of evidence addresses the improved efficacy of EGFR inhibitors in limiting glioblastoma tumor growth when used together with radiation, or with a histone deacetylase inhibitor, or with the mTOR inhibitor rapamycin." (PMID 40332381, 2025).
glioblastoma (continued). "Our results illustrated this limitation: in the first experiment, the two cancer cell populations detected by scEVE were characterized by EGFR, a known glioblastoma marker gene." (PMID 40491972, 2025). "EGFR (epidermal growth factor receptor) is a receptor tyrosine kinase (RTK) that regulates cell survival, growth, proliferation and differentiation in response to extracellular signals, and aberrant activation of EGFR is frequently observed in glioblastoma." (PMID 41145413, 2025). "One of the key drivers of glioblastoma progression is the dysregulation of several critical signaling pathways, including those involving the EGFR and the phosphatidylinositol-3-kinase (PI3K)/mammalian target of rapamycin (mTOR) axis." (PMID 40650170, 2025). "Overexpression and activation of EGFR regulate its downstream signaling pathways to drive development and progression of glioblastoma." (PMID 41145413, 2025). "The combination therapy of OV‐IL15C (an oncolytic virus expressing protein that includes human IL‐15 and IL‐15Rα sushi domain) and EGFR‐CAR NK cells exhibited synergistic effects over individual monotherapies in glioblastoma." (PMID 40859900, 2025). "Here, we applied the platform to a cetuximab backbone to generate the final product, Fc-engineered cetuximab (Pin-EGFR)-armed NK cells, and demonstrated its superior in vitro potency against EGFR-expressing cancer cells, focusing on glioblastoma cells." (PMID 39996727, 2025). "Tumors now classified as glioblastoma (formerly “primary GBM”) typically present de novo and exhibit epidermal growth factor receptor (EGFR) amplification, PTEN mutations, and chromosome 10 loss." (PMID 41301809, 2025). "eccDNAs carrying multiple copies of EGFR in glioblastoma and MYC in small-cell lung cancer have been shown to promote excessive proliferation and resistance to targeted therapies." (PMID 41311372, 2025). "IHC-wild type astrocytoma Grade 2 or 3 should be diagnosed as glioblastoma even inabsence of characteristic histopathological findings if any one molecular alteration is present out of EGFR amplification/TERTpmutation/+7/-10." (PMID 41170123, 2025). "EGFR gene amplification is found in approximately 40–60% of all glioblastomas, leading to higher EGFR expression and poor prognosis." (PMID 40277764, 2025). "This heterogeneity partly explains the disappointing results of the Rindopepimut trial, a cancer vaccine targeting EGFR-mutant glioblastoma cells." (PMID 40191211, 2025). "This study provides evidence that CAR T-cell therapy is an effective strategy for targeting multiple related antigens on glioblastoma cells and that EGFR is a viable immunotherapeutic target." (PMID 39941829, 2025). "EGFR represents an antigen frequently overexpressed in glioblastoma but also expressed in normal tissues." (PMID 41154636, 2025). "The signature was present in 60% to 70% of glioblastoma cases and frequently co-occurred with epidermal growth factor receptor amplification and telomerase reverse transcriptase promoter mutations." (PMID 41594781, 2025). "To demonstrate this feature, we specified EGFR vIII (exons 2–7 deletion), a known oncogenic driver in glioblastoma, in the target output file when analyzing FFPE samples from 35 glioblastoma cases (mean age 54.8 years, male 65.7%)." (PMID 40041857, 2025). "The expression of EGFR was determined by Hobbes and colleagues in another study using another antibody, 3C6, in 532 patients with glioblastoma." (PMID 40227788, 2025). "Despite their limited success in treating glioblastoma, EGFR-targeted treatments are still developing thanks to new compounds and delivery methods." (PMID 41311621, 2025). "Clinical data confirm the high expression of EGFR compared to normal tissues, especially in glioblastoma multiforme, as well as head and neck cancers, which include tongue squamous cell carcinoma, and slightly lower in prostate cancer." (PMID 40438187, 2025).
glioblastoma (continued). "This strategy enabled the virus to selectively direct the production of CCL5 to EGFR-expressing tumor cells within the glioblastoma microenvironment." (PMID 40867316, 2025). "Five studies were included to analyze the association between EGFR amplification and PFS in glioblastoma patients." (PMID 40331985, 2025). "The use of CAR-T cells in glioblastoma is based on targeting the tumor-specific or tumor-enriched antigens like IL-13Rα2, EGFR/EGFRvIII, HER2, CD70, B7-H3, and CD133/CD44." (PMID 41208963, 2025). "In adult HGGs, the EGFR gene is the most frequently amplified, with approximately one-third of glioblastomas exhibiting EGFR gene rearrangements." (PMID 40113789, 2025). "In glioblastoma cells, EGFR signalling promotes the cleavage and nuclear translocation of SREBP1, inducing FAS and ACC expression, with EGFRvIII mutant cells exhibiting increased fatty acid abundance and ACC phosphorylation." (PMID 39433211, 2025). "Six of nine candidate retention element intervals in the EGFR ecDNA in GBM39 glioblastoma neurospheres are significantly demethylated compared to all other sequence intervals of 1 kb width on the same ecDNA." (PMID 41278658, 2025). "In glioblastoma, eccDNAs carrying EGFR drive sustained receptor tyrosine kinase signaling, while in lung cancer, eccDNAs amplify MYC and promote chromosomal instability and cell division." (PMID 41311372, 2025). "In brief, primary glioblastomas showed a high level of proteins (and phospho-proteins) involved in cell division, mRNA processing, mitosis, and DNA damage repair driven by EGFR signaling." (PMID 40332381, 2025). "In this study, we uncover SPRY2-dependent bypass signaling mechanisms in glioblastoma that contribute to resistance against EGFR and MET (hepatocyte growth factor receptor) inhibition." (PMID 41567627, 2025). "The importance of the EGFR signaling pathway in the pathogenesis of glioblastoma is described in the literature." (PMID 40650170, 2025). "Immunohistochemical analysis showed the presence of EGFR expression in rat 101.8 glioblastoma samples taken from animals." (PMID 41473440, 2025). "While adult glioblastoma resistance typically develops from EGFR amplification or MGMT promoter methylation, pediatric H3K27M-mutant tumors evade treatment by employing chromatin remodeling and disrupted developmental processes (e.g., PRC2 dysfunction)." (PMID 40564017, 2025). "EGFRvIII is a constitutively active, ligand-independent mutant of EGFR, best characterized in glioblastoma, where it promotes tumor aggressiveness, intratumoral heterogeneity, and resistance to conventional therapies." (PMID 40472740, 2025). "This design aimed to enhance structural stability and tumor-targeting precision, particularly for glioblastoma models expressing the wild-type epidermal growth factor receptor (EGFR) and EGFRvIII." (PMID 41003524, 2025). "For this study, LASSBio-1971 was selected from the LASSBio® laboratory’s chemical library to be used as a prototype developed as an irreversible EGFR inhibitor, with proven potency in melanoma, breast, pancreatic tumors, and glioblastoma cell lines." (PMID 40650170, 2025). "Previous studies showed that EGFR amplification correlates significantly with peritumoral edema in glioblastoma." (PMID 40941753, 2025). "Conversely, glioblastomas with EGFR amplification are typically diffuse and infiltrative, necessitating a delicate balance between maximal resection and functional preservation." (PMID 40806492, 2025). "Approximately half of the isocitrate dehydrogenase (IDH)-wildtype glioblastomas (GBMs) exhibit EGFR amplification." (PMID 39959305, 2025).